RASL10A (RAS like family 10 member A)
Description:
Potent inhibitor of cellular proliferation.
Synonyms: RRP22
Tractability: Antibody: UniProt places it where antibodies can reach, with high confidence; its Gene Ontology location is reachable by antibodies, with medium confidence.
Gene: Protein-coding gene on chromosome 22 (29,312,933 to 29,319,679, reverse strand). Ensembl gene ENSG00000100276.
Subcellular location: Cell membrane; Nucleus, nucleolus
Gene Ontology:
Molecular function: GTPase activity; G protein activity; GTP binding
Biological process: small GTPase-mediated signal transduction
Cellular component: nucleolus; plasma membrane
Genetic constraint (gnomAD): Loss-of-function variants: 13 observed, 10.8 expected, observed/expected ratio (o/e) 1.2, 90% interval 0.78 to 1.8. The synonymous counts are far from expectation, so gnomAD's model fits this gene poorly and the ratio says little. Missense variants: 307 observed, 244.53 expected, observed/expected ratio (o/e) 1.26, 90% interval 1.14 to 1.38. Synonymous variants: 159 observed, 111.29 expected, observed/expected ratio (o/e) 1.43, 90% interval 1.25 to 1.63.
Homologues: Orthologues: chimpanzee RASL10A (100% identical), macaque RASL10A (99% identical), dog RASL10A (97% identical), guinea pig RASL10A (96% identical), pig RASL10A (96% identical), mouse Rasl10a (95% identical), rat Rasl10a (95% identical). Paralogues in human: RASL10B (52% identical), RASD1 (30% identical), RASD2 (30% identical), DIRAS2 (29% identical), DIRAS1 (26% identical), DIRAS3 (25% identical), RALB (25% identical), RAP1A (24% identical), RAP1B (24% identical), REM1 (24% identical), RERGL (24% identical), ERAS (24% identical), and 23 more.
Diseases named in the same sentence as RASL10A in open-access papers:
RASL10A is named in the same sentence as 4 diseases in open-access papers, as found by Europe PMC text mining. Sharing a sentence is not in itself a finding about the gene and the disease. The quoted sentences say what the papers report.
Parkinson disease (1 paper, 2024). A progressive degenerative disorder of the central nervous system characterized by loss of dopamine producing neurons in the substantia nigra and the presence of Lewy bodies in the substantia nigra and locus coeruleus. "RASL10A participated in GO BP pathways such as cytoplasmic translation, epithelial cell morphogenesis, and oxidative phosphorylation, while its KEGG pathways included olfactory transduction, Parkinson's disease, and ribosomes." (PMID 39498440, 2024).
tumor (5 papers, 2012 to 2025). "Moreover, it has been demonstrated that most neuronal tumor cell lines lose Rasl10a expression and that Rasl10a has a tumor suppressor potential." (PMID 24146943, 2013). "However, evidence that RASL12 functions as a small GTP-binding protein is lacking; In fact, studies have reported that RASL12 could be homologous to the RAS-like GTPases RERG, RASL11A, RASL11B, RASL10A and RASL10B, which play tumor-suppressive roles in human cancers." (PMID 34819106, 2021).
RASL10A also shares sentences with these, for which no sentence is quoted: cancer (1 paper); glioma (1).